LGI1 (leucine rich glioma inactivated 1)
Diseases named in the same sentence as LGI1 in open-access papers (continued):
Sharing a sentence is not in itself a finding about the gene and the disease.
Seizure (32 papers, 2018 to 2025). A seizure is an intermittent abnormality of nervous system physiology characterized by a transient occurrence of signs and/or symptoms due to abnormal excessive or synchronous neuronal activity in the brain. "The present study demonstrated for the first time that the astrocytic Kir4.1 expression was reduced in the Lgi1-related seizure model, suggesting that the down-regulation of Kir4.1 channels in astrocytes is involved in audiogenic epileptogenesis caused by Lgi1 mutation." (PMID 30813600, 2019). "Seizures were present in almost two-thirds of these patients, and in the anti-LGI1 mAb-positive cases they were most likely to be focal and of temporal origin." (PMID 39984135, 2025). "Seizure resolution in our LGI1 cohort was common, with 30.7% of patients being seizure-free with the use of ASMs and 64.2% without using ASMs noted after at least 2 years of follow-up." (PMID 40470500, 2025). "Anti-LGI1 patients mostly presented behavioral and psychiatric changes, seizures, and memory disturbances." (PMID 37954587, 2023). "Total IgG obtained from the pooled sera of NMDAR and LGI1-IgG positive patients with epileptic seizures and healthy subjects was applied chronically every other day for 11 days into the cerebral lateral ventricle." (PMID 38035091, 2023). "In our cohort, the anti LGI1/CASPR2 group displayed similar clinical profiles mainly consisting in seizures, memory impairment and behavioral changes." (PMID 36831042, 2023). "Seizures occur in the majority of patients with LGI1 antibodies, and radiologic evidence of mesial temporal sclerosis can be found late in the disease course." (PMID 37239077, 2023). "Epileptic seizures and LGI1 hypo-functions have been found in both ADLTE, a genetic epileptogenic syndrome and LGI1 limbic encephalitis (LE), an autoimmune disease." (PMID 35984846, 2022). "Patients with LGI1 LE exhibited epileptic seizures known to be due to an hyperexcitability and hypersynchronous activity of the neuronal network." (PMID 35984846, 2022). "In the anti‐LGI1 group, memory dysfunction and seizures were the most common symptoms, followed by psychiatric disturbance, altered consciousness, sleep disorders, autonomic dysfunction, and speech disorders." (PMID 32783406, 2020). "Seizures were frequent in LGI1 (90%), NMDAR (89%) and CASPR2 (4/5) AE." (PMID 36831042, 2023). "Seizure severity was significantly higher in the NMDAR-IgG and LGI1-IgG groups as compared to HC-IgG and saline groups only after PTZ treatment." (PMID 38035091, 2023). "Epileptic seizures might have different semiology, including facio-brachial dystonic seizures (FBDS) and pilomotor seizures, such as in anti- leucine-rich glioma inactivated-1 (LGI-1-IgG) AIE." (PMID 35794773, 2023). "Anti-LGI1 mAbs augmented the excitability of CA3 pyramidal neurons and elicited convulsive and non-convulsive spontaneous epileptic seizures in mice and rats." (PMID 39984135, 2025). "Our previous study divided the seizure semiology of anti‐LGI1 AE into three types: FBDS‐only, epileptic seizures without FBDS, and FBDS plus epileptic seizures; this method of analysis revealed differences, such as ictal discharges, among the types." (PMID 34291554, 2021). "In a recent study, patients with LGI1 AE were divided into the following three groups based on seizure semiology: FBDS only (FBDS-only), epileptic seizure without FBDS (non-FBDS, mainly manifested MTLE-like semiology), and coexistence of FBDS and other seizure (FBDS+)." (PMID 32431657, 2020).
Encephalopathy (27 papers, 2016 to 2025). Encephalopathy is a term that means brain disease, damage, or malfunction. "An earlier cross-sectional report on 51 patients with TS did not detect any specific serum autoantibodies associated with encephalopathies (targeting LGI1, CASPR2, NMDAR, AMPA1/2, GABAB1/B2)." (PMID 33041996, 2020). "Faciobrachial dystonic seizures (FBDS) followed by encephalopathy and memory loss were present in both anti-LGI1 patients." (PMID 31139134, 2019). "Limbic encephalitis with autoantibodies to LGI1 is associated with a distinct neuro-immunological clinical phenotype characterized by facio-brachial dystonic seizures progressing to cognitive and memory impairment, focal seizures and encephalopathy." (PMID 39984135, 2025). "However, the LGI1-associated disease spectrum spans from patients with FBDS only to patients with severe encephalopathies, and less persistent aggressive treatment is often appropriate; PLEX or IVIg with oral steroids is successful in many patients, although some require second-line therapies." (PMID 26692392, 2016). "Here, we present a case of a patient who presented after a suicide attempt with a long history of psychiatric issues, aberrant “spasms,” and subsequently encephalopathy, who was eventually diagnosed with anti-LGI1 LE only after delayed CSF antibodies studies." (PMID 39006729, 2024). "A 71-year-old male patient was diagnosed with LGI1 encephalopathy 4 weeks following a first ChAdOx1 nCov-19 vaccination." (PMID 35718786, 2022). "In one of our patients, the bradycardia led to sinus arrest, requiring placement of a pacemaker, 2 months prior to the development of encephalopathy and subsequent LGI1-IgG evaluation." (PMID 36304459, 2022). "Psychiatric symptoms, seizure, cognitive symptoms and encephalopathy were common presentations across the anti-LGi1, anti-Caspr2, anti-GABABR and anti-SOX1 subgroups." (PMID 33692738, 2021). "The inpatient encephalopathy, autoimmune evaluation, and spinal fluid 2 assay confirmed the anti-LGI-1 antibody in her CSF." (PMID 34437034, 2021). "A highly distinctive seizure semiology described as faciobrachial dystonic seizures (FBDS) precedes the development of frank encephalopathy in a proportion of cases with LGI1 antibodies." (PMID 26667479, 2016). "Alternatively, a CNS action of LGI1 antibodies may mediate pain consistent with observations including the frequent concurrent encephalopathy, striking binding to CNS tissue, and the truncal distribution reminiscent of central cord syndromes." (PMID 34370313, 2021). "Morvan syndrome is defined by the co-occurrence of encephalopathy and peripheral nerve hyperexcitability (irregular muscle contractions, fasciculations, and cramping), insomnia, hyperhidrosis and is frequently seen with LGI1 and Caspr2 autoantibodies." (PMID 34305787, 2021). "Both LGI1 and CASPR2 antibody-associated encephalopathies respond well to prompt immunotherapy, although residual amnestic deficits are common and may occur as a function of time to treatment in LGI1 antibody encephalopathy." (PMID 26667479, 2016). "Two patients in our center (case 1 and case 2) had various clinical syndromes involving CNS (encephalopathy and sleep disorders), PNS (pain), and autonomic 19 nervous system symptoms (hyperhidrosis, tachycardia, and hypertension) as well as serum and CSF LGI1 and CASPR2 antibodies." (PMID 35463890, 2022). "However, tremor can occur as part of an autoimmune encephalitis, and has been described with various antibodies typically in the context of a widespread encephalopathy: AMPAR-, CASPR2-, LGI1-, DPPX-, GABAR-B-, GlyR-, mGluR1-, NMDAR-, and GFAP-antibodies." (PMID 33324912, 2020). "Nevertheless, 3 of the 6 patients (50%) with both CASPR2 and LGI1 antibodies had many features of Morvan syndrome, including thymoma; however, none had developed encephalopathy, and the diagnosis remained NMT." (PMID 30242309, 2018).
neuromyotonia (27 papers, 2012 to 2025). "Among the VGKC complex antibodies evaluated with cell-based assays, anti-CASPR2 alone, or both anti-CASPR2 and anti-LGI1 antibodies, as observed in the present case, are frequently associated with Isaacs syndrome." (PMID 40718168, 2025). "Antibodies targeting CASPR2 and LGI1 have been associated with limbic encephalitis and neuromyotonia; the latter is characterized by peripheral nerve hyperexcitability." (PMID 40519393, 2025). "LGI1 antibody seems to be more strongly associated with limbic encephalitis than Isaacs' syndrome and less seropositive in Isaacs' syndrome compared with CASPR2 antibody." (PMID 31156543, 2019). "In another study, Vincent suggested that LGI1 might be associated with symptoms of acquired neuromyotonia." (PMID 40535121, 2025). "Anti-CASPR2 and anti-LGI1 antibodies should be evaluated in patients with Isaacs syndrome after thymectomy." (PMID 40718168, 2025). "Antibodies against LGI1 are strongly associated with limbic encephalitis, whereas antibodies against CASPR2, alone or occasionally with LGI1 antibodies, are frequently observed in patients with Morvan syndrome and Isaacs syndrome." (PMID 40718168, 2025). "Herein, we report the first case of Isaacs syndrome with anti-LGI1 and anti-CASPR2 antibodies that developed after thymectomy for myasthenia gravis." (PMID 40718168, 2025). "This patient exhibited symptoms of Isaacs syndrome as well as Guillain-Barré-like features, expanding the phenotypic spectrum associated with CASPR2 and LGI1 autoimmune syndromes." (PMID 37933002, 2023). "But it is a rare Isaacs syndrome with LGI1 and CASPR2 antibodies after human papilloma virus (HPV) vaccination." (PMID 37933002, 2023). "Not only detected in Isaacs' syndrome, both LGI1 and CASPR2 antibodies can also be discovered in other diseases, such as Morvan's syndrome, neuropathic pain, epilepsy, limbic encephalitis, and cerebellar dysfunction." (PMID 31156543, 2019). "Five/268 (2%) had neuromyotonia, four with typical autoantibodies, including LGI1 (n = 1), CASPR2 (n = 1) or both (n = 2)." (PMID 30714278, 2019). "In contrast, patients with LGI1 or CASPR2 antibodies often have clinically-indistinguishable late-onset forms of limbic encephalitis and neuromyotonia with associated dysautonomia, sleep disturbances, pain and seizures." (PMID 29788256, 2018). "Isaacs syndrome is peripheral nerve hyperexcitability characterized by spontaneous muscle twitching and rigidity and is often associated with antibodies to CASPR2 (contactin-associated protein-like 2) and LGI1 (leucine-rich glioma-inactivated 1)." (PMID 37933002, 2023). "His Isaacs’ syndrome is correlated well with the LGI1 antibody level." (PMID 35246046, 2022). "From 31 patients (28/31 with limbic encephalitis, including 12/31 with FBDS, 1/31 FBDS only, 1/31 Morvan’s syndrome, 1/31 neuromyotonia/pain), median serum autoantibody levels to membrane-tethered full-length LGI1 were 80-fold higher than CSF, consistent with peripheral antibody generation." (PMID 32437528, 2020). "Our findings contribute to the expanding phenotypic spectrum of CASPR2 and LGI1 autoimmune syndromes, suggesting that these 2 antigens, particularly CASPR2, may potentially serve as novel target antigens and be implicated in the etiology of Isaac syndrome." (PMID 37933002, 2023). "Three patients had Netrin‐1 receptor antibodies, two with neuromyotonia and concomitant CASPR2+LGI1 antibodies and one with spontaneous muscle overactivity without electromyography evidence of neuromyotonia." (PMID 30714278, 2019). "Marked clinical overlaps between patients with either anti-LGI1 or anti-CASPR2 antibodies include frequent focal seizures, prominent amnesia, dysautonomia, neuromyotonia, and neuropathic pain." (PMID 31178819, 2019). "We highlight marked clinical overlaps between patients with either LGI1 or CASPR2 antibodies that include frequent focal seizures, prominent amnesia, dysautonomia, neuromyotonia and neuropathic pain." (PMID 29055902, 2018).
neuromyotonia (continued). "PNH, which typically manifests as neuromyotonia, is considerably more common in CASPR2 compared to LGI1 autoimmunity, possibly due to the higher expression of CASPR2 in peripheral nerves compared to LGI1." (PMID 41008569, 2025). "In addition, some patients with LGI1 antibodies have isolated seizures including FBDS, Morvan’s syndrome, and a few have pain and neuromyotonia." (PMID 32437528, 2020). "FBDS were exclusive to patients with LGI1 antibodies (P < 0.0001) who had more seizures (P = 0.01) than patients with CASPR2 antibodies, where peripheral nerve features of neuromyotonia (P = 0.0003) and neuropathic pain (P < 0.0001) were preferentially associated." (PMID 29788256, 2018). "Although he tested negative for anti-LGI1 and anti-CASPR2 antibodies, we diagnosed him with Isaacs syndrome due to myokymic discharges on electromyography and symptoms being relieved by intravenous methylprednisolone (IVMP) and intravenous immunoglobulin (IVIg)." (PMID 36381695, 2022).
Autoimmunity (25 papers, 2015 to 2025). The occurrence of an immune reaction against the organism's own cells or tissues. "Limbic encephalitis (LE) associated with anti-LGI1 antibodies is an autoimmune disorder characterized by memory decline, behavioral changes, and temporal lobe epilepsy." (PMID 40407616, 2025). "IL‐17A has previously been implicated in neurological autoimmunity, including in LGI1‐AE, with CSF IL‐17A levels previously shown to correlate with disease severity in the acute phase." (PMID 40781580, 2025). "In less than 10% of cases, LGI1 autoimmunity is linked to malignancy, such as small cell lung cancer and thymoma, with an associated dearth of data on its incidence." (PMID 39734683, 2024). "The most frequent and best characterized NSAS are anti-N-methyl-D-aspartate receptor (NMDAR) encephalitis, and autoimmunity with NSAbs targeting the leucine-rich, glioma-inactivated protein-1 (LGI1), and the contactin-associated protein-2 (CASPR2)." (PMID 35515348, 2022). "We here provide a deep, comprehensive characterization of autoimmunity in a large and representative cohort of untreated patients with LGI1- and CASPR2-AIE, focusing on B- and T-cell interaction and shared components between CSF and blood." (PMID 40094812, 2025). "To provide arguments for causality over association of this MAIT-cell phenotype, we performed murine experiments to confirm functionally that MAIT cells influence systemic humoral anti-LGI1/anti-CASPR2 autoimmunity." (PMID 40094812, 2025). "This convergence of evidence from both connectivity and morphometric analyses strongly implicates these limbic structures as key targets of LGI1 autoimmunity." (PMID 40688080, 2025). "As regards the associated tumors, anti-LGI1 diseases are rarely paraneoplastic, whereas a tumor, mostly a thymoma, can be detected in 20–30% of patients with CASPR2 autoimmunity." (PMID 34659082, 2021). "The leucine-rich glioma inactivated 1 protein is encoded byLGI1, primarily locates at neuronal synapses and dysregulation of this protein due to LGI1 autoimmunity has been directly associated with limbic encephalitis." (PMID 35028426, 2021). "About 30% of patients with CASPR2 or LGI1 have other autoimmune disorders, including MG and thyroid disorders, in accordance with the presence of strong HLA associations in patients developing LGI1 and/or CASPR2 antibodies." (PMID 34439654, 2021). "Of greater relevance to a HLA study, patients with LGI1 or CASPR2 antibodies often had co-existent autoimmune conditions (28% and 23%, respectively), including Hashimoto’s thyroiditis (n = 8), psoriasis (n = 7) and pernicious anaemia (n = 2)." (PMID 29788256, 2018). "In summary, the distinct HLA associations in patients with LGI1 and CASPR2 autoantibodies, together with differing clinical features relating to autoimmunity, support an immunological dissociation in generation of these clinically-overlapping autoantibody-mediated syndromes." (PMID 29788256, 2018). "However, temporal association of detection of arrythmias with onset of neurological dysfunction and demonstration of LGI1 protein expression in the cardiac tissue supports the presence of this rare but potentially fatal cardiac manifestation of LGI1 autoimmunity." (PMID 36304459, 2022). "Administration of these exosomes to mice resulted in generation of antibodies targeting NMDAR, AMPAR, GABABR, LGI1, and CASPR2, indicating a potential role of exosomes in the development or maintenance of autoimmunity." (PMID 39473143, 2024). "Anti-NMDAR, anti-LGI1, and anti-CASPR2 autoimmunity represent the most described forms, while other NSAS are rarer and less well-characterized, especially in children." (PMID 35515348, 2022). "Animal models and genetic mutations in humans provide valuable opportunities to understand the molecular and clinical features of LGI1 and CASPR2 autoimmunity." (PMID 29055902, 2018).
Autoimmunity (continued). "In a review of CASPR2 and LGI1 autoimmunity in pediatric patients, 37.8% (14/37) patients had anti-LGI1 Abs, 37.8% (14/37) had anti-CASPR2 Abs, and 24.3% (9/37) patients were double-positive for anti-LGI1 and anti-CASPR2 Abs." (PMID 37274200, 2023). "Patients with anti-VGKC Abs on radioimmunoassays without concomitant detection of CASPR2 or LGI1 Abs were classified as possible rather than probable pAE cases, because this finding lacks a high specificity for autoimmunity." (PMID 35046526, 2022). "Recently, painful manifestations of LGI1 and CASPR2 autoimmunity have been highlighted." (PMID 34659082, 2021). "Examination of serum + CSF neural autoimmune encephalitis antibody was negative, which included NMDA-R-Ab, LGI1-Ab, CASPR2-Ab, GABAB-R-Ab, GAD65-Ab, AMPA1-R-Ab, and AMPA2-R-Ab." (PMID 36158962, 2022).